CRP (C-reactive protein)
Diseases named in the same sentence as CRP in open-access papers (continued):
Sharing a sentence is not in itself a finding about the gene and the disease.
lymphoproliferative disorders (1 paper, 2023). "In the context of CVDs in patients with lymphoproliferative disorders, several serum biomarkers have been suggested for risk stratification, including pro-B-type natriuretic peptide (proBNP), high-sensitivity C-reactive protein (hs-CRP), troponins, and brain natriuretic peptide (BNP)." (PMID 38033434, 2023).
macular edema (1 paper, 2023). "An increase in C-reactive protein is associated with increased risks of clinically severe macular edema and DR65,66." (PMID 37816862, 2023).
malaise (1 paper, 2016). A feeling of general discomfort or uneasiness, an out-of-sorts feeling. "Other clinical findings included malaise, elevated ESR (4/35 cases), or elevated C-reactive protein (11/35 cases)." (PMID 27999664, 2016).
maxillary sinusitis (1 paper, 2025). An acute or chronic inflammatory process affecting the mucous membrane of the maxillary sinus. "Based on the sinus CT scan findings (signs of bilateral maxillary sinusitis), some dynamics of CRP increase, intensification of catarrhal symptoms, it was decided to start empirical systemic antibacterial therapy (intravenous ceftriaxone)." (PMID 39850109, 2025).
metastatic squamous cell carcinoma of the (1 paper, 2024). "This study investigates the prognostic value of C-reactive protein (CRP) kinetics in patients with recurrent or metastatic squamous cell carcinoma of the head and neck (R/M-HNSCC) treated with checkpoint inhibitors (CPI)." (PMID 39001486, 2024).
microcephaly (1 paper, 2015). A congenital or acquired developmental disorder in which the circumference of the head is smaller than normal for the person's age and sex. "The risk of microcephaly was increased in newborns with hyperEPO+ISSI (ISSI defined by CRP, SAA, MPO, IL-6, TNF-α, TNF-R2, IL-8, MCP-1, ICAM-1, E-SEL, red), often more prominently than for ISSI alone." (PMID 25793991, 2015).
middle cerebral artery infarction (1 paper, 2021). Necrosis occurring in the middle cerebral artery distribution system which brings blood to the entire lateral aspects of each cerebral hemisphere. "The median CRP levels were 0.18, 0.51, and 0.18 mg/dL in patients with middle cerebral artery infarctions, posterior cerebral artery infarctions, and embolic infarctions, respectively." (PMID 34135849, 2021).
midgut volvulus (1 paper, 2022). "Heart rate, mean arterial pressure, serum C-reactive protein, serum sodium, serum albumin, and pH levels were independent predictors for intestinal ischemia and necrosis in patients with midgut volvulus." (PMID 35795333, 2022). "The constructed nomogram model, which combines the HR, MAP, serum CRP, albumin, serum sodium levels, and pH values, can be a superior tool for predicting intestinal ischemia and necrosis in neonates with midgut volvulus." (PMID 35795333, 2022).
mycosis fungoides (1 paper, 2024). Classical mycosis fungoides is the most common type of mycosis fungoides (MF), a form of cutaneous T-cell lymphoma, and is characterized by slow progression from patches to more infiltrated plaques and eventually to tumors. "He had neutrophilic leukocytosis (18.610 cells/μL), his c-reactive protein was 27 mg/dL, and his skin lesions from mycosis fungoides were just starting to improve." (PMID 39194909, 2024).
nasal cavity tumors (1 paper, 2025). "Furthermore, CRP was not significantly elevated and thus not diagnostically useful in dogs with nasal cavity tumors with cribriform plate lysis." (PMID 40260215, 2025).
necrosis (1 paper, 2019). The phenotypic observation that death has occurred in groups of cells or in one or more tissues due to external factors, such as infection, toxins, mechanical trauma, loss of blood supply and other injuries (e.g. corrosion or burning). "CK-MB and cTnT are both direct biomarkers of myocardial necrosis, which are potentially associated with CRP." (PMID 31523180, 2019).
neoplastic polyp (1 paper, 2024). "The fact that CRP, an important indicator of systemic inflammation, is found to be higher in neoplastic polyps suggests that they may be related to the inflammatory response." (PMID 39459558, 2024). "In particular, inflammatory parameters such as CRP, albumin, PLR, CALLY index, HALP score, PIV, SIII, and SIRI were significantly different in neoplastic polyps compared to nonneoplastic polyps." (PMID 39459558, 2024).
neurofibroma (1 paper, 2022). An intraneural or extraneural neoplasm arising from nerve tissues and neural sheaths. "Because the inflammation localized in neurofibromas may not sufficiently stimulate signals for the production of common inflammation markers such as C-reactive protein, the assessment of inflammation by CBC testing in NF1 may have rarely been a focus before now." (PMID 36335228, 2022).
neuroleptic malignant syndrome (1 paper, 2023). Neuroleptic malignant syndrome (NMS) is an idiosyncratic condition associated with administration of antipsychotic and other central dopaminergic blockers, and characterized by hyperthermia, muscular rigidity, autonomic dysfunction and altered consciousness. "In some patients, neuroleptic malignant syndrome is accompanied significant high levels of erythrocyte sedimentation rate (ESR), C‐reactive protein (CRP)." (PMID 37546158, 2023).
neurosyphilis (1 paper, 2025). Infection of the brain or spinal cord by Treponema pallidum. "This study evaluates the predictive value and clinical significance of CXCL13, WBC, and Hs-CRP levels in neurosyphilis patients undergoing HBO and TUS-NMES therapy." (PMID 40070668, 2025).
otitis externa (1 paper, 2022). Inflammation of the anatomical structures of the outer ear and ear canal secondary to an infectious process. "Neither CRP nor erythrocyte sedimentation rate were useful in identifying those with definite necrotising otitis externa." (PMID 35042578, 2022). "In contrast to a report in the early necrotising otitis externa literature, our data showed that elevated CRP, not erythrocyte sedimentation rate was significantly associated with complex disease." (PMID 35042578, 2022).
ovarian serous cystadenocarcinoma (1 paper, 2019). A malignant serous cystic epithelial neoplasm arising from the ovary. "We further examined the expression patterns of Cyr61, IL-6, CRP and neutrophil percentage in peripheral blood of patient with early or advanced stage of ovarian serous cystadenocarcinoma." (PMID 31766991, 2019).
Paraproteinemia (1 paper, 2023). An abnormal immunoglobulin or part of an Ig (light chain) in the circulation. "Even if, typically, conditions like paraproteinemia were to affect ESR, it cannot be excluded that even CRP test results can be affected if its specific diagnostic assay can be affected, too." (PMID 37873776, 2023).
parathyroid disease (1 paper, 2023). "On the contrary, a study concluded that the mean serum concentrations of IL-6, CRP, and ESR had increased one year after surgical cure of the parathyroid disease (p < 0.001, p < 0.01, and p < 0.001, respectively)." (PMID 37858254, 2023).
paroxysmal nocturnal hemoglobinuria (1 paper, 2023). Paroxysmal nocturnal hemoglobinuria (PNH) is an acquired clonal hematopoietic stem cell disorder characterized by corpuscular hemolytic anemia, bone marrow failure and frequent thrombotic events. "Studies on paroxysmal nocturnal hemoglobinuria and CRP are limited, and notably elevated CRP values can be seen in some case reports—possibly in relapses." (PMID 37873776, 2023).
pasteurellosis (1 paper, 2019). Infections with bacteria of the genus pasteurella. "Laboratory investigations revealed elevated leukocytes, C-reactive protein levels, and liver enzymes in all patients who died from pasteurellosis." (PMID 30666933, 2019).
penicillin allergy (1 paper, 2020). "CRP level, penicillin allergy, mandibular molar infection, psychiatric disorders and immunodepression allow us to characterize four profiles of patients linked to a risk level higher than 25% to need several surgical interventions and to have complex course." (PMID 33266250, 2020). "For that reason, CTREE analysis was constructed based the only objective criteria as CRP level, penicillin allergy, immunodepression, mandibular molar infection and psychiatric disorders." (PMID 33266250, 2020). "The study highlighted specific clinical symptoms of severity (such as oropharyngeal oedema, floor oedema, fever and trismus), penicillin allergy, psychiatric disorders and CRP level as predictors of complex evolution." (PMID 33266250, 2020).
perianal Crohn disease (1 paper, 2021). A Crohn disease involving a pathogenic inflammatory response in the anal region. "Disease activity was measured with the Perianal Crohn’s Disease Activity index (PDAI) and serum C-reactive protein (CRP)." (PMID 34829482, 2021).
periostitis (1 paper, 2016). Inflammation of the periosteum. "Laboratory tests that help differentiate cGVHD from periostitis include ALP level, CRP, CK, and rheumatologic testing." (PMID 27403356, 2016).
peripheral nerve lesion (1 paper, 2020). "It is subdivided into two types: CRP type I (no peripheral nerve lesions) or type II (definable nerve lesion)." (PMID 32132973, 2020).
peripheral vertigo (1 paper, 2020). "One study reported that serum d-dimer, fibrinogen, and C-reactive protein levels were not useful for differentiating central and peripheral vertigo." (PMID 32266274, 2020).
phlebitis (1 paper, 2018). Inflammation of a vein. "The phlebitis ointment reduced the levels of necrosis factor-α, interleukin-6, C-reactive protein, and interleukin-1ß." (PMID 29849699, 2018). "In conclusion it can be stated that the phlebitis ointment reduced the levels of necrosis factor-α, interleukin-6, C-reactive protein, and interleukin-1ß." (PMID 29849699, 2018).
pituitary adenomas (1 paper, 2023). "The full blood count (FBC), the C-reactive protein (CRP), the albumin and the serum inflammation-based scores have been investigated as markers of systemic inflammation in patients with pituitary adenomas/PitNets." (PMID 36658300, 2023).
pituitary diseases (1 paper, 2023). "In hypopituitary patients and in patients with other pituitary diseases the highest CRP levels were 14.2 mg/L (1.42 mg/dL) and 14.9 mg/L (1.49 mg/dL), respectively (data not shown)." (PMID 37122698, 2023).
pityriasis rosea (1 paper, 2008). A mild, self-limited skin disorder that is most commonly seen in children and young adults. "We undertook a study to investigate the role of Streptococcus haemolyticus in the causation of pityriasis rosea and study the levels of C-reactive protein (CRP) and ASLO titer in patients with pityriasis rosea." (PMID 19882027, 2008).
placental disorders (1 paper, 2012). "The rise of AST/GOT and of CRP in women with risk of abortion constitutes an indicator of utero-placental disorders." (PMID 22574089, 2012).
plasma cell dyscrasias (1 paper, 2013). "CRP values, instead, were within the normal range in the present case, suggesting that CRP could be a more specific index of AAION in patients with coexisting plasma cell dyscrasias." (PMID 24359546, 2013).
pleurisy (1 paper, 2024). "Patients with PCI with pleurisy presented an important inflammatory syndrome, with high values of the average concentration of CRP and with an average of LDH above the reference interval." (PMID 38392603, 2024).
Pneumocephalus (1 paper, 2025). Presence of air or gas within the intracranial cavity (e.g., epidural space, subdural space, intracerebral, etc.) which may result from traumatic injuries, fistulous tract formation, erosions of the skull from NEOPLASMS or infection, NEUROSURGICAL PROCEDURES, and other conditions. "Pneumocephalus, elevated CRP levels, and low CSF glucose may serve as predictors of poor prognosis." (PMID 40809603, 2025).
post-thrombotic syndrome (1 paper, 2025). A condition characterized by a chronically swollen limb, often a leg with stasis dermatitis and ulcerations. "Interestingly, while inflammation is known to be involved in thrombosis and vascular injury, inflammatory markers such as CRP and D-dimer were not significantly different between patients with and without post-thrombotic syndrome, suggesting that local, rather than systemic, inflammation may be key." (PMID 40871683, 2025).
posterior uveitis (1 paper, 2023). Inflammation of the choroid as well as the retina and vitreous body. "Further investigations into the relationship between vitreous IL-6 levels and clinical parameters including gender and CRP for the diagnosis and prognosis of posterior uveitis are needed." (PMID 36902507, 2023). "Considering this study, there may be a relationship between vitreous IL-6 concentration and serum CRP expression levels in posterior uveitis as well." (PMID 36902507, 2023).
postherpetic neuralgia (1 paper, 2022). "Among them, the erythrocyte sedimentation rate, CRP level, CGRP level, and interleukin-6 level of group B were significantly lower than those of group A. The incidence of postherpetic neuralgia (PHN) in group B patients (6.25%) was also lower than that in group A patients (25%)." (PMID 35450055, 2022).
proctocolitis (1 paper, 2023). Inflammation of the rectum and colon. "Another study showed that serum CRP was notably higher in food protein-induced enterocolitis syndrome (FPIES) than in food protein-induced proctocolitis (FPIP), suggesting its utility as a marker for differentiating the pathogeneses of these conditions." (PMID 37873776, 2023).
progeria (1 paper, 2022). "This theory is supported by the finding that, in the SAMP8 mouse strain (a progeria model), spleen weight and CRP levels were associated with a reduction in IL-6 and IL-6R expression in bone tissues as compared to a wild type control strain." (PMID 36458163, 2022).
prostate tumors (1 paper, 2023). "Importantly, CRP was not significant in three studies of patients with prostate tumors on ADT, whereas fibrinogen was not significant in one report." (PMID 37213604, 2023).
protein-misfolding diseases (1 paper, 2025). "We analyze the clinical significance of variations in CRP levels in patients with protein-misfolding diseases, discuss underlying mechanisms, and highlight potential implications of these findings for drug discovery and therapeutic targeting of CRP." (PMID 40534869, 2025). "This review aims to provide a comprehensive overview of the current understanding of CRP’s involvement in neurodegenerative diseases and other protein misfolding disorders." (PMID 40534869, 2025).
pulmonary stenosis (1 paper, 2021). "In a study of post-operative outcomes in TOF, pre-operative factors such as severity of pulmonary stenosis and higher C-reactive protein levels were associated with complicated post-operative course, but pre-operative ventricular functional parameters were not taken into account." (PMID 34368247, 2021).
Pythiosis (1 paper, 2021). A granulomatous disease caused by the aquatic organism PYTHIUM insidiosum and occurring primarily in horses, cattle, dogs, cats, fishes, and rarely in humans. "Further studies are needed to evaluate efficacy of treatment modalities and to understand patterns of ESR and CRP in pythiosis patients, particularly with relapse or disseminated disease." (PMID 33557064, 2021).
radiation syndrome (1 paper, 2025). "During the acute radiation syndrome phase, biomarkers like C-reactive protein, platelet count, and hemoglobin reflected systemic inflammation and hematopoietic impairment." (PMID 40862205, 2025).
Rathke cleft cyst (1 paper, 2023). "We retrospectively examined the association between GH secretion, assessed using GH-releasing peptide-2, and serum hs-CRP levels before and a year after the pituitary surgery in patients with nonfunctioning pituitary neuroendocrine tumor or Rathke cleft cyst." (PMID 38024646, 2023).
rectal adenocarcinoma (1 paper, 2009). "Cell accumulation of C-reactive protein was observed in 65 (71%) out of 91 patients with rectal adenocarcinoma and in all 22 control cases (p < 0.01)." (PMID 27956962, 2009). "Cellular accumulation of CRP was observed in 65 (71%) out of the 91 patients with rectal adenocarcinoma and in all 22 controls (p < 0.01)." (PMID 27956962, 2009). "Cell expression of CRP was observed in 65 of the 91 patients with rectal adenocarcinoma and in all control samples." (PMID 27956962, 2009). "We investigated immunohistochemically whether C-reactive protein is expressed in human primary rectal adenocarcinoma and assessed its relationship with clinicopathological findings." (PMID 27956962, 2009).
Rectal prolapse (1 paper, 2020). Protrusion of the rectal mucous membrane through the anus. "In contrast, the concentrations of CRP in pigs suffering from lameness (48.88 ng/mL) and rectal prolapse (51 ng/mL) appeared increased compared to clinically healthy pigs." (PMID 32000745, 2020). "Some markers were more pronounced in a specific condition, such as Cu or Cd in healthy animals or CRP and Hp in rectal prolapse or lameness, while other markers were lacking, such us ADA or CRP in healthy animals or Cu in all pathological conditions." (PMID 32000745, 2020).
Renal amyloidosis (1 paper, 2025). A form of amyloidosis that affects the kidney. "Tocilizumab, an antibody blocking the IL-6 receptor, has stabilized or improved the kidney function of patients with renal amyloidosis, more so in patients with active inflammation and CRP above the baseline." (PMID 41375725, 2025).
Renal artery stenosis (1 paper, 2023). The presence of stenosis of the renal artery. "TAK patients with CAL had significantly higher CRP,WBC, PLT,TNF-α and IL-2R levels (P < 0.05), lower HGB (P = 0.01), lower rate of renal artery stenosis (RAS) (P = 0.009)." (PMID 37118779, 2023).
renal hypertension (1 paper, 2025). Hypertension caused by the kidney's hormonal response to narrowing or occlusion of the renal arteries. "Their levels correlated positively with disease activity (SLEDAI), inflammation (CRP), and renal damage indicators (BUN, Scr, cystatin C, urine α1-MG, and renal hypertension)." (PMID 40988967, 2025).
renal tubular acidosis (1 paper, 2024). A group of genetic disorders of the kidney tubules characterized by the accumulation of metabolically produced acids with elevated plasma chloride, hyperchloremic metabolic acidosis. "ESSDAI, European League Against Rheumatism Sjögren’s Syndrome Disease Activity Index; ITP, immune thrombocytopenia; RTA, renal tubular acidosis; ESR, erythrocyte sedimentation rate; CRP, C-reactive protein." (PMID 38627838, 2024).
retinal (1 paper, 2020). "For example, we found that retinal microaneurysms (FDR-adjusted p ≤ 0.0001), the most statistically significant retinal lesions in individuals with DR, is already correlated with some of the variables such as HbA1c, CRP, BUN, beryllium, and haematocrit, suggesting early effects." (PMID 33198349, 2020).
Retinal hemorrhage (1 paper, 2020). Bleeding located within the retina. "CD can improve retinal microneuropathy, retinal hemorrhage, exudates, and whole blood viscosity, by a mechanism related to the decrease of serum endothelin-1 and high-sensitivity C-reactive protein levels." (PMID 32963587, 2020).
retinal ischemia (1 paper, 2025). A ischemic disease that involves the retina. "Reverse causation is possible (e.g. retinal ischemia could induce systemic inflammation), and unmeasured confounders may influence both CRP and DR." (PMID 41159344, 2025).
retinal vasculitis (1 paper, 2023). Inflammation of the retinal vasculature with various causes including infectious disease; lupus erythematosus, systemic; multiple sclerosis; behcet syndrome; and chorioretinitis. "When CRVO occurs in a young patient, it is important to evaluate for inflammatory markers by assessing biologic inflammatory indicators (such as ESR, CRP, serum protein electrophoresis, and fibrinogen) and performing FA to assess for retinal vasculitis." (PMID 37601780, 2023).